MTOR (mechanistic target of rapamycin kinase)
Diseases named in the same sentence as MTOR in open-access papers (continued):
Sharing a sentence is not in itself a finding about the gene and the disease.
cancer (continued). "We further investigated the indirect link between these cancer hallmarks genes and circadian drug targets in our datasets and identified AKT1 and MTOR as potential circadian drug targets for both of our cell lines." (PMID 32295075, 2020). "Overall, we suggest that mLST8 constitutes a potential target for cancer therapy as a cross‐road between STAT3 and the mTOR pathway." (PMID 32495998, 2020). "mTOR activates hypoxia-inducible factor 1 (HIF-1) and initiates the c-Myc-hnRNPs–mediated alternative splicing, which leads to aerobic glycolysis in cancer cells." (PMID 32195169, 2020). "Based on the proteoglycans in cancer pathway, we found that genes positively related to COL8A1 participate in the VEGF and mTOR signaling pathways, which have been identified as targets of TNBC treatments." (PMID 32818022, 2020). "Also, in the case of the common adaptogen Rhodiola rosea L., effects on the mTOR pathway could be experimentally demonstrated, as its major active constituent salidroside was shown to alleviate cachexia symptoms in mouse models of cancer cachexia via activating mTOR signaling." (PMID 32733236, 2020). "mTOR is primarily involved in regulating the NOX4, which are involved in cancer-related signaling and are closely related to the occurrence and development of tumours." (PMID 33335853, 2020). "PI3K/AKT/mTOR pathway is commonly accepted as a vital pathway in controlling cancer progression, and lncRNA as ceRNA has been validated to mediate tumorigenesis and development through PI3K/AKT/mTOR pathway." (PMID 32231464, 2020). "Similar to other cancers, PI3K/AKT/mTOR pathway is hyperactive in MCC and inhibition of this pathway has demonstrated significant anti-MCC effects in vitro and in vivo as reported in this study and by others." (PMID 32483262, 2020). "In particular, metformin has been shown to modulate AMP-activated protein kinase (AMPK) activation via LKB1 with consequent inhibition of the mTOR pathway, which is crucial in cell growth and proliferation in CRC as in other cancer types." (PMID 32977434, 2020). "During tumor development, abnormal triggering of the phosphatidylinositol -3-kinase (PI3-K), Akt, the mammalian target of rapamycin (mTOR) and the STAT3 survival pathways is usually observed in many cancer cell types." (PMID 32401800, 2020). "The pseudokinase Tribbles homologue 2 (TRIB2) has been characterized as an important driver of resistance to several anti-cancer drugs, including the dual ATP-competitive PI3K and mTOR inhibitor dactolisib (BEZ235)." (PMID 33316942, 2020). "Targeted inhibition of the PI3K/AKT/mTOR signaling axis triggers activation of the MST kinase and inhibits activity of YAP effector in a broad spectrum of cancer cells." (PMID 32375238, 2020). "CXCL12 binds to CXCR4 and CXCR7 to promote cancer progression and promotes chemoresistance invasion and migration by activating a number of intracellular signaling molecules, including Akt, EGFR, mTOR, NF-κB, and Src." (PMID 32963527, 2020). "One of the largest superclusters was composed of 22 nt 3′-tRFs upregulated in 13 cancer types, all of which share the activation of Ras/MAPK, RTK and TSC/mTOR signaling." (PMID 34316691, 2020). "LYN inhibition increases cancer cell apoptosis, and reduces cancer cell proliferation, migration, and invasion, likely by inactivating the WNT/Beta-Catenin and AKT/mTOR pathways and activating the mitochondrial apoptotic pathway." (PMID 33233470, 2020). "For example, a group of 3′-tRFs with precise 22 nt was found coincidentally upregulated across a majority of (13/15) cancer types, all of which share the activation of Ras/MAPK, RTK and TSC/mTOR signaling." (PMID 34316691, 2020).
cancer (continued). "The activation of autophagy by naringin inhibited cancer cell growth and it was achieved through the downregulation of the PI3K/Akt/mTOR pathway via activation of MAPKs." (PMID 32927836, 2020). "Pathway enrichment analysis of these data identified alternations in multiple cancer-related signaling pathways including PI3K and mTOR as well as AMPK and apoptosis induction." (PMID 32795346, 2020). "Thus, the Akt/mTOR pathway may be regarded as a promising therapeutic target for cancer treatment." (PMID 32850379, 2020). "Gene Ontology and KEGG pathway analyses of the target genes were performed, and several key signaling pathways (mTOR, Hippo, MAPK, AMPK, and PI3K-Akt signaling pathways, as well as miRNAs in cancer and focal adhesion) were regulated." (PMID 32049961, 2020). "Combination therapy has been shown to achieve higher efficacy; such as the combination of HT with mTOR inhibitors or CDK4/6 inhibitors are used for tumors with enhanced mTOR signaling and for CDK4/6 sensitive cancer, respectively." (PMID 32545494, 2020). "For instance, murine studies show that aerobic exercise regulates the Protein Kinase B/mammalian target of rapamycin (AKT/mTOR) signaling pathway which is a key cell growth regulator and is hyperactivated in many cancer types." (PMID 33207085, 2020). "In cancer cells, EZH2 epigenetically represses Deptor, an inhibitor of the mammalian target of rapamycin (mTOR) pathway." (PMID 32508971, 2020). "This pathway is aberrantly expressed in many cancers including NB12,13,47, however, mTOR/Akt inhibitors have yet to provide robust tumour control." (PMID 33262374, 2020). "Deeper insight in relations between mTOR pathway and GEM activity in cancer cells makes interpretation of obtained results even more complex." (PMID 33173419, 2020). "The first link between AMPK and cancer was identified through the tumor-suppressive function of LKB1, which is upstream of the mTOR pathway." (PMID 32807122, 2020). "Among them, the phosphatidylinositol 3-kinase/protein kinase B/mammalian target of rapamycin (PI3K/AKT/mTOR) and MAPK signaling pathways are crucial for autophagosome formation in cancer cells." (PMID 32576196, 2020). "Taken together, our findings indicated that lncRNA HUMT promotes cancer cell proliferation, lymph node metastasis, and lymphangiogenesis by HUMT/YBX1/FOXK1-mediated Akt/mTOR and VEGFC signaling." (PMID 32138762, 2020). "The secreted cytokines from macrophages can trigger PI3K/AKT/mTOR signaling pathway and also lead to the activation of NFKB as well as STAT3 in cancer cells." (PMID 32883235, 2020). "Whereas many of the recommendations for cancer treatment relate to cytotoxic chemotherapy, guidance on newer therapies, e.g., immune checkpoint CDK4/6, mTOR, and PARP inhibitors, appears only intermittently." (PMID 33330049, 2020). "Bioinformatic analysis demonstrated that differentially expressed miRNAs were associated with pathways regulating metabolism, survival, and cancer development such as the PI3K-Akt, ErbB, mTOR, and MAPK, insulin signaling pathways." (PMID 33133155, 2020). "The Mammalian Target of Rapamycin (mTOR) pathway is a downstream signaling pathway that can be regulated by the AKT, and was widely studied in the field of cancer for issues such as tumorigenesis, metastasis, and therapy." (PMID 33613618, 2020). "Accumulating evidence has revealed that the PI3K/AKT/mTOR pathway plays important roles in relaying PTEN signalling in GIST and the neoplastic lipogenesis of other cancers." (PMID 31957165, 2020). "PI3K/Akt/mTOR and Ras/Raf/MEK/ERK pathways are two of the most commonly dysregulated signaling pathways in TNBC and other cancers." (PMID 32503622, 2020). "The over-expression of KLF5 promotes cancer cell survival and hypoxia-induced cisplatin resistance through the activation of the PI3K/Akt/mTOR pathway." (PMID 32252351, 2020).
cancer (continued). "A set of triterpenoids demonstrate the ability to reduce phosphorylation levels of the mechanistic target of rapamycin (mTOR) and mTOR/AKT/PI3K pathway that lead to delay in aging and aging-related disorders (including cancer and neurodegeneration)." (PMID 32560451, 2020). "Further KEGG analysis suggested that the potential targets of miR-410 were involved in cancer-related pathways, including Ras, PI3K/Akt, mTOR, and Wnt." (PMID 32528035, 2020). "In most of the cancer cells, the PI3K (phosphoinositide 3-kinase)/mTOR (mammalian target of rapamycin) signaling pathway is activated by insulin, thereby up-regulating PKM2 expression through HIF1α-mediated transcription of the PKM gene." (PMID 32195169, 2020). "Our results showed that two well-known drug target genes in cancer therapy, AKT1 and mTOR were oscillating in both CRC cell lines." (PMID 32295075, 2020). "Recently early-phase trials showed that PI3K/AKT/mTOR inhibitors appear promising for the treatment of PIK3CA and PTEN altered tumors based on 1,656 patients from MD Anderson cancer center." (PMID 32101536, 2020). "The second largest group was mTOR, RAF1, and MAPK1-related kinases, which are involved in cancer cell metabolism and signal transduction." (PMID 32944406, 2020). "TRIB2 confers resistance to several anti-cancer drugs, including the PI3K/mTOR inhibitor BEZ235, by inactivating the AKT/FOXO signaling axis." (PMID 33316942, 2020). "In thyroid cancer, CBS is the major responsible for H2S production, which activates cancer cells proliferation and migration, through ROS/PI3K/AKT/mTOR and MAPK pathways." (PMID 32714858, 2020). "Epigenetic modifiers participate in the PI3K/Akt/mTOR pathway, contributing to the oncogenicity of PI3K in cancer." (PMID 32932888, 2020). "Activation of mTOR is commonly observed in many types of cancer cells and metformin is well recognized for its effects on the activation of AMPK, followed by the inhibition of mTOR." (PMID 33194743, 2020). "What is interesting is that +mTOR is both an OXPHOS cancer therapeutic target and a glycolysis cancer therapeutic target." (PMID 32276228, 2020). "Metformin has been shown to increase the sensitivity cancer cells to oxidative stress and therapeutic drugs, through AMP-activated protein kinase (AMPK) and the mechanistic target of rapamycin (mTOR) pathway." (PMID 32927432, 2020). "Flow cytometry analysis confirmed that mTOR is located downstream of PI3K/Akt and is the main pathway for CKI to regulate cancer cells." (PMID 32020871, 2020). "CQ is the autophagy inhibitor most widely used in cancer, and currently the only autophagy modulator (except from PI3K/AKT/mTOR inhibitors) under clinical evaluation for CCA." (PMID 32143356, 2020). "As mTOR signaling is activated in the majority of cancers, several inhibitor compounds, inhibiting either PI3K or mTOR or both, have been developed during the last decade." (PMID 32455578, 2020). "The PI3K/AKT/mTOR signaling pathway regulates cancer cell proliferation, migration, survival, and angiogenesis, and AKT1 and mTOR genes have been identified as targets of miR-99a-3p in other types of cancers." (PMID 32842533, 2020). "The up-regulation of lncRNA PVT1 increased the expression of MDR1, MRP, mammalian target of rapamycin (mTOR) and hypoxia-inducible factor alpha (HIF-1α) and decreased the apoptosis produced by cisplatin in BGC823 and SGC7901 cancer cells." (PMID 32164712, 2020). "Fourthly, PI3K/Akt also activates the downstream regulator of the mammalian target of rapamycin (mTOR) to further activate HIF-1α, so as to promote aerobic glycolysis, angiogenesis and neo-vascularization in cancer cells." (PMID 32631382, 2020). "Phosphoinositide 3-kinase/protein kinase B/mammalian target of rapamycin (PI3K/AKT/mTOR) signaling pathway is a crucial controller of cellular growth and survival that is commonly upregulated in cancer." (PMID 32222803, 2020).
cancer (continued). "Previous work in cancer cells demonstrated that both the translation and activity of PDCD4 can be regulated via the mTOR-p70S6K pathway, prompting us to investigate the potential link between PDCD4 and its upstream regulator p70S6K." (PMID 32747606, 2020). "This phenotype mirrors the behavior of several angiogenesis-addicted cancers, in which laboratory and angiogenesis-markers related to the VHL and mTOR (mammalian target of rapamycin) pathway are also shared." (PMID 32456352, 2020). "It was shown that curcumin exhibits anti-cancer effect in several tumour models through regulating PI3K/Akt/mTOR pathway whereby it suppresses the Akt activation along with downstream targets, mTOR." (PMID 32131560, 2020). "The Ras/Raf/MEK/ERK and PI3K/Akt/mTOR signaling pathways crosstalk with the Hippo/YAP signaling pathway and negatively regulate Hippo kinases to activate the oncogenic function of YAP in cancer cells." (PMID 32466572, 2020). "Oncoviruses can lead to the onset and progression of cancer via commonly shared pathways including WNT/β-catenin, JAK/STAT/SRC, PI3k/Akt/mTOR, and/or RAS/MEK/ERK signaling pathways." (PMID 32521661, 2020). "The reconstruction of pathways around estrogen receptor (ER), mTOR and cyclin D allowed the comparison of the effects of CDK4/6 and PI3K/AKT/mTOR inhibitors in metastatic HR+ cancer." (PMID 32351542, 2020). "As a critical mechanism of cancer progression and metastasis, the EMT process involves various pathways, which includes PI3K/AKT/mTOR, RAS/RAF/MEK/ERK, Wnt/β-catenin, and Transforming Growth Factor-β (TGF-β)." (PMID 33202380, 2020). "GSEA analysis revealed that the differentially expressed genes were mainly involved in cancer cell proliferation, PI3K-Akt-mTOR, therapy resistance, and tumorigenesis." (PMID 33234130, 2020). "The known main mechanisms of platin resistance reported to date include cancer stem cells (CSCs), epithelial-to-mesenchymal transition (EMT), abnormal DNA repair-related pathways, and the NF-κB and PI3K/AKT/mTOR signaling pathways." (PMID 32066429, 2020). "Previous works have demonstrated the beneficial effects of Myr against different types of cancer, through the inhibition of protein kinases in distinct intracellular signaling pathways such as PI3K-PKB/Akt/mTOR, MEK1, Fyn and JAK1-STAT3, among others." (PMID 32276584, 2020). "Research has identified several biological processes which contribute to the radiosensitisation of cancer, following PI3K/AKT/mTOR pathway inhibition." (PMID 32443649, 2020). "The PI3K/AKT/mTOR pathway affects tumorigenesis through eIFs, reported in HCC, GC, CRC, and other cancer types." (PMID 33066449, 2020). "Earlier studies in cancer confirmed miR-21 and miR-221 mediated AKT/PTEN/mTOR signaling cascade activation by western blot." (PMID 33614488, 2020). "In a cholangio induced carcinoma model, deletion of Fyn repressed carcinoma cell migration and invasion through regulating the AMPK/mTOR signaling pathway." (PMID 32565740, 2020). "The enriched pathways of Module 0 were related mainly to classical cancer pathways, such as Ras, PI3K-Akt, or mTOR signaling in KEGG and integrins in angiogenesis in NCI-PID." (PMID 31119098, 2019). "To address this, we combined eribulin with BEZ235 or BKM120, two pan-class PI3K/AKT/mTOR inhibitors that induce pathway inhibition and show anti-tumor activity in PI3K-pathway-dysregulated cancers." (PMID 31480338, 2019). "In many human cancers, the PI3K/Akt/mTOR pathway is activated through VEGF and plays an important role in regulating angiogenesis." (PMID 30871059, 2019). "The other pathways are associated with cell cycle, development, immune response, and other cancer- related pathways (B-Raf, NGF, mTOR/MAPK and WNT signaling)." (PMID 31216276, 2019).
cancer (continued). "A dual blockade of mTOR and other PI3K pathway inhibitors results in synergistic decreases in cancer cell growth." (PMID 31480338, 2019). "For instance, combinatorial treatment targeting mTOR and EGFR has been successful in other cancers, including small cell lung cancers." (PMID 30970654, 2019). "The PI3K/AKT/MTOR axis is an important target for molecular abnormalities in both ASD and cancer, which makes it a good candidate to modulate putative comorbid ASD and cancer associations." (PMID 31007884, 2019). "Accordingly, co-inhibition of PI3K/mTOR and JAK2 synergistically reduced cancer cell number and tumour growth, and also decreased tumour metastatic spread." (PMID 35582276, 2019). "Dual blockade of mTOR and other PI3K pathway inhibitors results in synergistic decrease in cancer cell growth." (PMID 31703728, 2019). "For instance, H2O2 emerges a key mediator in inducing both cancer initiation, via activation of PI3K-Akt-mammalian target of rapamycin (PI3K-Akt-mTOR) axis, and metastasis, via activation and stabilization of HIF1α during hypoxia." (PMID 31491919, 2019). "Inhibition of mTOR can be achieved by rapamycin, also known as sirolimus, or its analogs, so-called rapalogs, that are FDA approved to treat advanced cancer." (PMID 31137815, 2019). "This is concordant with the recent reports on the synergistic anti-cancer activity of combined CDK4/6 and mTOR targeting." (PMID 31388935, 2019). "The Warburg effect is the ability of cancer cells to shift the generation of ATP from oxidative phosphorylation to glycolysis and can be regulated by the AKT/mTOR pathway." (PMID 30713602, 2019). "In most cancer cell lines, fucoidan treatment resulted in a decrease in phosphorylated PI3K, AKT and mTOR." (PMID 30621045, 2019). "BEZ-235 is a dual PI3K-mTOR inhibitor that can target activation of PI3K and mTOR kinases and has been actively used against various cancers." (PMID 30813295, 2019). "In recent years, many cancer studies have described the crosstalk between the CXCR4/SDF-1 axis and the Akt/mTOR pathway and demonstrated the inhibitory effect of CXCR4 antagonist (AMD3100) on mTOR expression." (PMID 32047724, 2019). "Targeting the EMT signaling axis via AKT2/TWIST and PI3K/AKT2/mTOR in order to revert EMT and restore the epithelial phenotype appears to be a promising strategy in cancer therapy." (PMID 31357505, 2019). "Proliferation and apoptosis of cancers are regulated by multi-signaling pathways, such as PI3K/AKT/mTOR, MAPK/ERK, and STAT3." (PMID 31178739, 2019). "We also found additional noteworthy pathways enriched in NPC, such as pathways in cancer, ERBB, PI3K, Ras, and mTOR signaling pathway by using the DAVID tool, that are frequently targeted by genetic abnormalities in NPC." (PMID 30950204, 2019). "Ganetespib effectively suppresses cancer progression by inducing G2/M cell cycle arrest through inhibition of RAS/RAF/ERK and PI3K/AKT/mTOR pathways and promoting caspase-3-mediated apoptosis." (PMID 31878360, 2019).